CDK4 (cyclin dependent kinase 4)
Diseases named in the same sentence as CDK4 in open-access papers (continued):
Sharing a sentence is not in itself a finding about the gene and the disease.
multiple myeloma (27 papers, 2012 to 2025). "Multiple myeloma, the second most common hematopoietic cancer, exhibits deregulation of CDK4/6 that appears as the loss of cell cycle control." (PMID 39598723, 2024). "Palbociclib (PD0332991) selectively inhibits Cdk4/6, causing a G1 arrest in primary myeloma cells." (PMID 29163849, 2017). "The CDK4/6 inhibitor, abemaciclib, inhibits myeloma cell growth and exhibits cytotoxicity in a dose-dependent manner." (PMID 35127532, 2021). "In line, the specific Cdk4/6 inhibitor palbociclib was demonstrated to achieve better objective responses in myeloma patients compared to the pan-Cdk inhibitors flavopiridol, SNS-032 or dinaciclib." (PMID 29163849, 2017). "Specific miRNAs such as miR-29b and miR-34, which normally regulate the Cdk4/6 levels, are downregulated in myeloma resulting in this increased Cdk4/6 expression." (PMID 29163849, 2017). "HDACi has been shown to induce deregulation of cell cycle genes, cyclin D1 and Cdk4 leading to hypophosphorylation of pRb, thereby resulting in cell cycle arrest in multiple myeloma cells." (PMID 24586690, 2014). "The same outcome was observed in myeloma cells after inhibiting CDK4/6 activity." (PMID 40753072, 2025). "We identify a novel dual-targeting c-Myc inhibitor D347-2761 targeting c-Myc unstable domain and c-Myc/Max heterodimerization, which further inhibits myeloma growth and infiltration in vitro and in vivo via regulating downstream CDK4 promoter transcriptional activity." (PMID 35619182, 2022). "Based on preclinical data obtained for the Cdk inhibitors, it was suggested that specific Cdk4/6 inhibitors might be more favourable to use in anti-myeloma therapy than pan-Cdk inhibitors, since Cdk4/6 are the main Cdks deregulated in MM patients." (PMID 29163849, 2017). "Our studies identified a novel dual-targeting c-Myc inhibitor D347-2761, which could block c-Myc/Max heterodimerization and disturb c-Myc protein stability to further repress multiple myeloma growth in vitro and in vivo via inhibiting CDK4 promoter transcriptional activity." (PMID 35619182, 2022). "In addition to cyclin D overexpression, increased Cdk4 and Cdk6 are also described in myeloma." (PMID 29163849, 2017). "Likewise, myeloma cells treated with 20 μM orlistat exhibited a significant reduction in p21 and phospho-pRb levels in myeloma cells, whereas cyclin D1, cyclin D2, cyclin E, CDK4, CDK6, p16 and p27 remained unchanged." (PMID 23029529, 2012). "FOXM1’s interaction with NIMA-related kinase 2 (NEK2) and the CDK4/6-Rb-E2F axis, in myeloma cells, is considered to be useful from a therapeutic aspect, because CDK inhibition is thought to be effective in myeloma treatment." (PMID 32679860, 2020). "Of note, CCND2 myeloma cells overexpress CDK6 and CDK4 while CCND1 myeloma cells overexpress CDK4 but not CDK6, suggesting that CDK4 is “empty” of cyclin D in CCND2 myeloma cells." (PMID 30545397, 2018). "FOXM1’s interaction in myeloma cells with NEK2 (NIMA-related kinase 2) and the CDK4/6-Rb-E2F axis is of interest from a therapeutic viewpoint because CDK inhibition may be effective in myeloma." (PMID 30463534, 2018). "Our data imply that the effects of CDK6 in multiple myeloma depend on its kinase function but are independent of RB1, the CDK4/6 substrate which is most relevant for other cancers." (PMID 35197447, 2022). "For example, in multiple myeloma cells, APRIL promotes cell cycle progression in cyclin D2-positive cells by upregulating CDK4, CDK6, and phospho-retinoblastoma protein, but did not regulated cell-cycle proteins in cyclin D1-positive cells." (PMID 25826583, 2015).
leiomyosarcoma (26 papers, 2007 to 2026). An uncommon, aggressive malignant smooth muscle neoplasm, usually occurring in post-menopausal women. "Using the data from Kaplan Meier plotter and LOGpc, we noted that leiomyosarcoma patients who had an association of genomic alterations in CDK4, CCT2, and MGAT1 showed reductions in overall and disease-free survival." (PMID 32117430, 2019). "In mice, a favourable effect on leiomyosarcoma by CDK4 inhibition was observed." (PMID 30804704, 2019). "A recent large cohort study of 99 patients with LMS found that CDK4 may be a key gene for leiomyosarcoma recurrence, and palbociclib, an inhibitor of CDK4, may provide a new option for targeted therapy in patients with LMS." (PMID 32117430, 2019). "Out of all the leiomyosarcoma patients, 65.7% were positive for both CDK4 and CDK6." (PMID 30804704, 2019). "LPD showed CDK4, NBN, DAXX, MYC moderately, and strongly positive, and uterine leiomyosarcoma displayed strongly positive." (PMID 32359372, 2020). "The immunohistochemistry staining analysis of CDK4, MYC, NBN, and DAXX in uterine leiomyoma (10 cases), LPD (4 cases), and leiomyosarcoma (10 cases) was subsequently conducted." (PMID 32359372, 2020). "Oncomine analysis of cancer vs. normal tissue showed that cdk4, cct2, and MGAT1 were significantly overexpressed in leiomyosarcoma in the different datasets." (PMID 32117430, 2019). "CDK4 and MDM2 were also amplified during differentiation of myoblasts towards myotubes, in leiomyosarcoma and rhabdomyosarcoma." (PMID 29416732, 2018). "The IHC results for MDM2 and CDK4 were negative in leiomyosarcoma and positive in DDLPS in over 90% of the cases." (PMID 39588302, 2024). "In addition, in Brazilian cohorts, amplification or overrepresentation of CDK4 was evinced through qRT-PCR and immunoreactivity in both forms of RMS (ERMS and ARMS), along with several leiomyosarcoma samples." (PMID 36839989, 2023). "Comparison of uterine vs nonuterine leiomyosarcoma showed the following: Uterine tumour samples (n=46) were positive for CDK4, CDK6, and p-Rb in 65.2%, 87.2%, and 73.9%, respectively; 30.4% expressed ≤10% p16 protein." (PMID 30804704, 2019). "Indeed, combining an MDM2 antagonist and a CDK4 inhibitor resulted in an antagonistic effect in myxofibrosarcoma (IB114) and leiomyosarcoma (IB136) cells, indicating that the synergistic effect was specific to the DDLPS histological subtype." (PMID 28629371, 2017). "CDK4 and MDM2 were amplified in leiomyosarcoma and rhabdomyosarcoma." (PMID 26760505, 2016). "In the present case, the leiomyosarcomatous component showed no immunopositivity for MDM2 and CDK4; however, some leiomyosarcomas show positivity for MDM2 and CDK4." (PMID 23971887, 2013).
rhabdomyosarcoma (26 papers, 2013 to 2025). A rare aggressive malignant mesenchymal neoplasm arising from skeletal muscle. "CDK4 Amplification Reduces Sensitivity to Ribociclib in fusion-positive rhabdomyosarcoma." (PMID 37475713, 2023). "Regarding another rare tumor, alveolar rhabdomyosarcomas (RMS), amplifications at 12q13q14 and 2p24 have been described, leading to the overexpression of CDK4 and CDK6, among other genes." (PMID 38275873, 2024). "Studies of alveolar rhabdomyosarcoma cell lines and xenograft models RH28 and RH41 have shown reduced activity of CDK4/6i in cells that overexpress CDK4." (PMID 36595763, 2022). "Since rhabdomyosarcoma and peripheral malignant nerve sheath tumors, etc, can also abnormally express MDM2 and CDK4, and the sensitivity of p16 expression in DDLPS is 98%, combined detection of MDM2, CDK4, and p16 genes is often recommended to avoid misdiagnosis." (PMID 39606156, 2024).
leukopenia (25 papers, 2018 to 2025). "Letrozole and fulvestrant were considered the main concomitant therapy associated with CDK4/6 inhibitors both in suspected leukopenia and thrombocytopenia reports." (PMID 37895811, 2023). "The reported incidence rate of any grade fatigue, anorexia, and leukopenia was 50.8%, 45.9%, and 44.7% in patients treated with CDK4/6i." (PMID 37667421, 2023). "When a CDK4/6 inhibitor was used in combination with another drug therapy (fulvestrant, letrozole, anastrozole, or exemestane) the odds of serious cases of leukopenia decreased (OR = 0.294, 95% CI: 0.14–0.62)." (PMID 37895811, 2023). "When a CDK4/6 inhibitor was used in combination with another drug therapy (fulvestrant, letrozole, anastrozole, exemestane) the odds of serious cases of leukopenia decreased (OR = 0.294, 95% CI: 0.14–0.62) when compared to monotherapy." (PMID 37895811, 2023). "Spontaneous reports of CDK4/6 inhibitors related to hematological events—leukopenia and thrombocytopenia—were analyzed through a retrospective study conducted on data retrieved from the EV database." (PMID 37895811, 2023). "This work aims to describe the suspected adverse drug reactions (ADRs), such as leukopenia and thrombocytopenia, reported for each CDK4/6 inhibitor in the EudraVigilance (EV) database." (PMID 37895811, 2023). "According to the Summary of Product Characteristics (SmPC) of CDK4/6 inhibitors, leukopenia is considered a very common reaction in patients taking palbociclib, ribociclib and abemaciclib." (PMID 37895811, 2023). "A total of 822 ICSRs have been reported for leukopenia as suspected ADR and mentioning one CDK4/6 inhibitor as a suspected drug." (PMID 37895811, 2023). "Line of treatment seemed to be important for the occurrence of adverse events as patients treated in first line with CDK4/6 had less leukopenia (p = 0.03), but not any of the other adverse events (all p > 0.05) compared to patients treated in second line or beyond." (PMID 39338149, 2024).
mantle cell lymphoma (25 papers, 2013 to 2025). Mantle cell lymphoma is a rare form of malignant non-Hodgkin lymphoma affecting B lymphocytes in the lymph nodes in a region called the ``mantle zone''. "Overexpression of cyclin D1 and consequent activation of CDK4/6 is a hallmark of mantle cell lymphoma (MCL); the CDK4 inhibitor palbociclib has shown modest clinical activity but was found to sensitize MCL cells to PI3K inhibitors." (PMID 33401428, 2021). "A significant role of CDK4/6 kinases was reported in hematopoietic cancers, such as acute lymphoblastic leukemia or mantle cell lymphoma." (PMID 39598723, 2024). "There are now three FDA approved oral CDK4/6-inhibitors (CDK4/6i) which have shown single agent clinical activity in solid cancers, and in mantle cell lymphoma." (PMID 35082402, 2022). "In a single-arm study, five of 17 patients with relapsed mantle cell lymphoma remained progression-free for more than 1 year on CDK4/6 inhibitor therapy, with one complete response (CR) and two partial responses (PRs)." (PMID 28578693, 2017). "An in vitro study in mantle cell lymphoma revealed that the CDK4/6 inhibitor, PD-0332991, suppressed E2F1 expression." (PMID 25136922, 2014). "In this context, the frequent overexpression of CDK4/6 and their association with poor prognosis in diffuse large B-cell lymphoma (DLBCL) and mantle cell lymphoma (MCL) warrant further investigations on CDK4/6 inhibitors as potential therapeutic options for these patients (NCT01739309, NCT02414724)." (PMID 41388212, 2025). "These PROTACs also targeted Ikaros (IKZF1) and Aiolos (IKZF3) and showed enhanced antiproliferative effects in mantle cell lymphoma (MCL) cell lines when both CDK4/6 and IKZF1/3 were degraded simultaneously." (PMID 40793752, 2025). "ARV‐771 significantly suppressed tumor growth in vivo and improved the survival of mantle cell lymphoma (MCL)-cell-engrafted nude mice, and co-treatment with ARV-771 and ibrutinib or venetoclax (BCL2‐antagonists) or palbociclib (CDK4/6 inhibitor) synergistically induced apoptosis in MCL cells." (PMID 38389844, 2024). "Early phase I and phase II studies suggest that this drug is well tolerated and demonstrates efficacy in cancers that are driven by CDK4 and CDK6 such as mantle cell lymphoma." (PMID 24098593, 2013). "Besides CDK4 and CDK6, ON123300 and ON108110 inhibit PI3Kδ and CK2, respectively, and induced Rb dephosphorylation, G1 arrest, and apoptosis in mantle cell lymphoma." (PMID 34065376, 2021). "Mantle cell lymphoma (MCL) is an uncommon and invasive subtype of non-Hodgkin’s lymphoma, with a poor prognosis, derived from mature B cells that often do not enter the follicular germinal center and that often present aberrantly high cyclin D1-driven CDK4 activity." (PMID 36291856, 2022).
pancreatic ductal adenocarcinoma (25 papers, 2014 to 2025). An infiltrating adenocarcinoma that arises from the epithelial cells of the pancreas. "We show that the KRAS-G12C inhibitor Sotorasib synergizes with the CDK4/6 inhibitor Palbociclib to eliminate pancreatic ductal adenocarcinoma (PDAC) cells and organoids harboring KRAS-G12C mutations." (PMID 41436723, 2025). "In a pancreatic ductal adenocarcinoma cell model, CDK4/6 inhibition was associated with increased mTORC1 activity, which produces ATP accumulation at the mitochondrial level and induces drug resistance." (PMID 35463324, 2022). "Aberrant cell cycle machinery and loss of the CDKN2A tumor suppressor locus make CDK4/6 a potential target in pancreatic ductal adenocarcinoma (PDAC)." (PMID 32843618, 2020). "In preclinical models of KRAS-mutant pancreatic ductal adenocarcinoma, co-inhibition of CDK4/6 and MAPK signaling pathway improved treatment efficacy." (PMID 40317086, 2025). "In this article, we discuss the therapeutic potential of CDK4/6 inhibitors in pancreatobiliary cancers, notably cholangiocarcinoma and pancreatic ductal adenocarcinoma." (PMID 36765923, 2023). "The small molecule inhibitors targeting CDK4 and CDK6 recuperate the impaired tumor suppression function induced by p16INK4A mutation, which revives the tumor growth in pancreatic ductal adenocarcinoma (PDAC)." (PMID 37390335, 2023). "It has been reported that MEK therapy combined with cyclin-dependent kinase 4/6 (CDK4/6) inhibition promotes a proangiogenic SASP in KRAS-mutant pancreatic ductal adenocarcinoma." (PMID 35614034, 2022). "CDK4 inhibition was shown to decrease invasion, metastatic spread, and tumor progression in a RB-high pancreatic ductal adenocarcinoma model." (PMID 33723248, 2021). "In preclinical studies, CDK4/6 inhibitor, palbociclib, had an additive effect on cell death in pancreatic ductal carcinoma cell lines when combined with MEK or PI3K/mTOR inhibitors." (PMID 33806615, 2021). "Interestingly, recent work revealed that the combination of CDK4/6i and MEKi induces senescence in pancreatic ductal adenocarcinoma and suppressed tumor growth in Braf/MEK inhibitor-resistant melanoma." (PMID 39695080, 2024). "In addition, in combination with taxanes, sequential administration of CDK4/6 inhibitors prevented the proliferation of pancreatic ductal adenocarcinoma (PDAC) cells." (PMID 36457244, 2023). "A role for CDK4/6 in mitochondrial metabolism is also well supported, whereby increased oxidative mitochondrial metabolism is observed in pancreatic ductal adenocarcinoma cells treated with palbociclib, fuelled by increased glutamine consumption and metabolism." (PMID 33572972, 2021). "The same research group also examined the efficacy of CDK4/6 and MEK inhibition in Ras-driven pancreatic ductal adenocarcinoma (PDAC)." (PMID 40723291, 2025). "In Kras-mutant pancreatic ductal adenocarcinoma mice, dual inhibition of MEK and CDK4/6 can induce CS and improve the efficacy of anti-PD-1 therapy." (PMID 38972884, 2024). "The SASP generated by the combination of MEK and a CDK4/6 inhibitor induces the accumulation of CD8+ T cells and makes pancreatic ductal adenocarcinoma more sensitive to immune checkpoint blockade." (PMID 36612193, 2022). "Importantly, the oncogenic roles of CDK4/6 and YAP1 have been identified not only in HCC, but also in many other cancers, including breast cancer, esophageal cancer, pancreatic ductal adenocarcinoma." (PMID 40307228, 2025).
familial melanoma (24 papers, 2005 to 2025). Familial melanoma (FM) is a rare inherited form of melanoma characterized by development of histologically confirmed melanoma in two first degrees relatives or more relatives in an affected family. "Although the CDKN2A and CDK4 genes have been primarily linked to familial melanoma, the contribution of these genes only accounts for a small percentage of familial melanoma." (PMID 38275910, 2024). "This condition is more frequently observed in patients with genetic predispositions, such as mutations in CDKN2A and CDK4, which are commonly associated with familial melanoma." (PMID 39518584, 2024). "The tumor suppressors p16 (CDKN2A) and p15 (CDKN2B) (encoded by the familial melanoma CDKN2 locus) inhibit CDK4/6 activity and have important roles in cellular senescence." (PMID 32067956, 2020). "In addition, mutations in genes such as cyclin-dependent kinase inhibitor 2A (CDKN2A) and cyclin-dependent kinase 4 (CDK4) have been shown to be the most common genetic variants in familial melanoma." (PMID 37427124, 2023). "Moreover, a specific mutation of the CDK4 gene (CDKR24C) that confers resistance to p16 INK4a binding has been shown to play a causal role in rare cases of familial melanoma, suggesting that unchecked CDK4 activity is a key event in these cancers." (PMID 28418845, 2017). "Moreover, oncogene Cyclin‐dependent kinase 4 (CDK4) and TSG CDKN2A, which encodes p16INK4a, have been linked with familial melanoma progress." (PMID 40761498, 2025). "High penetrance genes associated with familial melanoma are CDKN2A and CDK4." (PMID 37895483, 2023). "Furthermore, this missense mutation did not segregate with the phenotype in familial melanoma, and is situated outside the critical four ankyrin repeat domains of p16, and thus does not appear to have any effect in vitro on binding to CDK4." (PMID 15928671, 2005). "While PVs have also been detected in several other genes, including CDK4, BAP1, ATM, MITF and multiple telomere stability genes TERT, POT1, ACD, and TERF21P, about half of the cases of familial melanoma remain unexplained." (PMID 40072281, 2025). "In particular, germline mutations convey pro-tumorigenic features and often affect the high-risk susceptibility genes CDKN2A and, less commonly, CDK4, associated with familial melanoma, where the phenotype of CDKN2A or CDK4-mutated families is indistinguishable." (PMID 34123788, 2021).